SMAD2 (SMAD family member 2)
Diseases named in the same sentence as SMAD2 in open-access papers (continued):
Sharing a sentence is not in itself a finding about the gene and the disease.
breast carcinoma (continued). "Therefore, as shown by our data, TGF-β1 could induce the sustained activation of Smad2/3 in non-invasive breast cancer cells in presence of H2O2 and LPS." (PMID 23734265, 2013). "In the TCGA breast cancer dataset, SDC1 expression was notably correlated with the stem cell biomarkers CD133, CD44, CD24, POU5F1, SMAD2, and NANOG at the transcriptional level." (PMID 41364407, 2025). "Previously, it was demonstrated in breast cancer (BC) cell lines grown as xenografts that SMAD2/3 signaling played a dominant role in mediating tumor suppressor effects on well-differentiated BC lines but pro-metastatic functions on a more invasive, metastatic BC cell line." (PMID 40134804, 2025). "Several genes found on chromosome 18, such as SMAD4, SMAD2, MIB1, and MBD1, are involved in breast cancer development and progression." (PMID 38803515, 2024). "SMAD4, SMAD2, SMAD3, SMAD7, SMAD1, SMAD6, and SMAD5 showed genetic variation in 1.8%, 1.2%, 1.1%, 0.8%, 0.7%, 0.6%, and 0.5% of patients with breast cancer, respectively." (PMID 38514720, 2024). "These include EMT (TWIST1, SNAIL1, RUNX1, RUNX2, HIF1, and NOTCH1), breast cancer maintenance (OCT4, SP1, GATA1, ATF1, FOXO3a, ELK1, VDR, and NRF1), pro-metastatic responses (SMAD2/3, HNF1a, GLI1, NANOG, YY1, MYB1, and AP1), and immune modulation (STAT1/3)." (PMID 38398186, 2024). "EW-7197 is a potent, selective, orally bioeffective TGFβ receptor ALK4/ALK5 inhibitor that can inhibit TGFβ-induced Smad2 or Smad3 phosphorylation and epithelial to mesenchymal transition (EMT) in TGFβ-treated breast cancer cells." (PMID 35794374, 2023). "The expression of SMAD2 and SMAD7 is associated with outcomes in breast cancer patients, for downregulated SMAD2 and SMAD7 promote breast cancer metastasis." (PMID 35461253, 2022). "For example, in the metastatic breast cancer cell model MDA-MB-231, Smad2 knock-down led to a more aggressive phenotype, while Smad3 knock-down led to a lag in tumor initiation, suggesting that Smad2 and Smad3 have opposing effects on disease progression." (PMID 35858839, 2022). "Further analyses using the GEPIA2 and TIMER2.0 databases revealed that NOLC1 was positively correlated with stemness-related genes, including MYC, ALDH18A1, ALDH1A1, SMAD2, SMAD3, etc., in both all breast cancer and TNBC." (PMID 35174077, 2022). "Some studies have pointed out that in breast cancer, TGFβ-activated kinase (TAK) catalyzes the phosphorylation of ACC and thereby activates the transcription of Smad2, ultimately influencing the metastasis of breast cancer." (PMID 36532744, 2022). "In breast cancer, DHA inhibits EMT by reducing TGF-β production and decreasing phosphorylation of Smad2 and Smad3." (PMID 34539408, 2021). "In breast cancer, TGF-β1/Smad2/3 signaling has been testified to promote the malignant progression of cancers cells." (PMID 34281492, 2021). "We previously reported the increased expression of DLX2 in human lung and breast cancer cell lines exposed to single IR at 8 Gy and these cells showed TGF-β-mediated EMT by Smad2/3 signaling." (PMID 33924205, 2021). "Several recent studies reported that SMAD2 promoted the tumor progression by upregulating the CDK2, CDK4, and cyclin E in metastatic breast cancer cells." (PMID 33330073, 2020). "Recently, it was reported that miR-486-5p inhibited EMT by down-regulating SMAD2 and EMT regulators, vimentin and E-cadherin in breast cancer." (PMID 33374139, 2020). "We also explored the functional coupling between activated SMAD2/3 and DICER1 to control the biogenesis of miR-615-3p in breast cancer." (PMID 32336285, 2020). "In breast cancer, TGF-β can stimulate EMT via Smad2 and Smad3 activation, leading to an increase in N-cadherin and vimentin levels, and a decrease in E-cadherin levels." (PMID 32752069, 2020). "Herein, we assess the role of PICK1 on the TGF-β signaling effectors SMAD2/3 and DICER1 in the processing of pre-miR-615-3p to yield mature miR-615-3p in breast cancer cells." (PMID 32336285, 2020).
breast carcinoma (continued). "The administration of Res suppresses the metastasis of breast cancer (under both in vitro and in vivo conditions) via the inhibition of TGF-β1 and down-regulation of Smad2 and Smad3." (PMID 32752069, 2020). "In suppressing malignant behavior of breast cancer cells, curcumin down-regulates expression of TGF-β1 to inactivate Smad2 and MMP-9." (PMID 33381035, 2020). "In summary, our findings suggest that miR-3613-3p acts as a cancer-suppressor miRNA and serves its anti-cancer function by inhibiting SMAD2 and EZH2 in breast cancer." (PMID 33330073, 2020). "The tumor suppressor miR-190 was found to suppress metastasis formation in breast cancer, by directly targeting SMAD2 and antagonizing TGFβ-induced EMT, creating a feedback-loop with TFGβ/SMAD2 signaling in controlling breast cancer EMT and metastasis." (PMID 32316552, 2020). "We found that miR-3613-3p was negatively correlated with the expression of SMAD2 and EZH2 in the breast cancer samples." (PMID 33330073, 2020). "As PSG9 enhances the stability of Smad2/3/4, there are two possibilities for the contribution of PSG9 to breast cancer cell proliferation and tumor growth." (PMID 33377651, 2020). "In breast cancer cells, TGFβ levels as well as the downstream expression of NRP1 and SMAD-2 are negatively regulated by microRNA (miR)-206, and overexpression of miR-206 inhibits EMT as well as migration and invasion of breast cancer cells." (PMID 30717262, 2019). "In breast cancer cells, TGFβ-YAP/TAZ-TEAD signaling is crucial in driving late-stage metastatic phenotypes via Smad2/3-induced NERG1 and UCA1 transcription." (PMID 31212916, 2019). "For example, pAMPK prevented TGF-β-mediated phosphoactivation of SMAD2 and/or SMAD3 in vascular smooth muscle and breast cancer cells." (PMID 31640193, 2019). "While the mechanisms through which breast cancer cells escape TGF-β mediated growth suppression are being pursued, we observed a consistent reduction in Smad2 protein in several human triple negative breast cancer cells relative to normal cells." (PMID 31798766, 2019). "Inhibition of TGF-β/SMAD2 has been shown to reverse the EMT-phenotype and suppress breast cancer metastasis." (PMID 29510731, 2018). "SMAD2, a positive regulator of TGF-β signaling, promotes breast cancer metastasis through induction of EMT." (PMID 29510731, 2018). "The TTB also attenuated the TGF-β1-induced Smad2 phosphorylation and epithelial to mesenchymal transformation (EMT), and suppressed breast cancer metastasis." (PMID 29796175, 2018). "Accumulated acetyl-CoA causes total protein acetylation, including acetylation of the signal transducer Smad2; this enhances Smad2 transcriptional activity and ultimately results in EMT and metastasis in breast cancer." (PMID 29996946, 2018). "In conclusion, SMAD2 downregulated CLDN6 via DNMT1 mediated DNA methylation to promote EMT, thereby accelerating the migration and invasion of breast cancer cells." (PMID 28867761, 2017). "Our data demonstrated that, in breast cancer cells, the low expression of CLDN6 was regulated by DNMT1 mediated methylation, which was in turn regulated by the SMAD2 pathway." (PMID 28867761, 2017). "After treating the two breast cancer cell lines with SB431542, a TGFβ type I receptor inhibitor that specifically inhibits SMAD2 and SMAD3 phosphorylation, which leads to down regulation of DNMT1 and upregulation of CLDN6." (PMID 28867761, 2017). "We have discovered that EGF-stimulated activation of Smad2/3 upregulated several key EMT markers, inhibited E-cadherin expression, promoted EMT, enhanced migration and invasion in MCF-7 and MDA-MB-231 breast cancer cells." (PMID 27829223, 2016). "In conclusion, EGF-induced EMT via phospho-Smad2/3-Snail pathway was a crucial event during the migration and invasion of MCF-7 and MDA-MB-231 breast cancer cells." (PMID 27829223, 2016). "Smad2/3 collaborate with TEAD and YAP to form an active transcriptional complex at CTGF promoter in breast cancer cells." (PMID 27759563, 2016).
breast carcinoma (continued). "Recent studies have shown that Nodal induces not only the Smad2/3 signaling pathway but also ERK1/2 signaling and PI3K/AKT signaling in breast cancer and melanoma, respectively." (PMID 25557170, 2015). "Next, we evaluated the effect of PEAK1 overexpression on TGFβ-induced Smad2/3, Src and MAPK signaling in MCF7 breast cancer cells." (PMID 26267863, 2015). "TGF-β, an important inducer of EMT, degrades NFI-C, whereas NFI-C induces dephosphorylation of p-Smad2/3, a TGF-β signaling molecule, in odontoblasts and breast cancer cells." (PMID 25879941, 2015). "Our data suggest that HRG-β1 and ErbB3 induce EMT, cancer cell migration and invasion through the PI3k/Akt-phospho-Smad2-Snail signaling pathway in SK-BR-3 and MCF7 breast cancer cells." (PMID 23937725, 2013). "Taken together, ErbB3 contributed to the HRG-β1-induced EMT process and cell migration through phospho-Smad2-mediated expression of Snail via the PI3k/Akt signaling pathway in SK-BR-3 and MCF7 breast cancer cells." (PMID 23937725, 2013). "Future studies need to address the role of CystC in regulating Smad2/3-independent signaling stimulated by TGF-β, as well as determining their contribution in preventing the oncogenic activities of TGF-β in human breast cancer cells." (PMID 16168131, 2005). "Moreover, DAB-2-28 inhibits the phosphorylation of key pro-EMT transcriptional factors, such as NFκB, STAT3, SMAD2, CREB, and/or AKT proteins, in breast cancer cells exposed to different EMT inducers." (PMID 40807456, 2025). "We observed that ENG suppression by shRNA in myCAFs not only attenuated TGF‐β‐Smad2/3 signaling and TGF‐β1 production but also inhibited the ability of these fibroblasts to promote tumor growth when co‐injected with human breast cancer cells subcutaneously into recipient mice." (PMID 40644310, 2025). "However, in breast cancer, inhibition of ACACA leads to the enhancement of Smad2 acetylation, ultimately resulting in epithelial-mesenchymal transition (EMT) and metastasis." (PMID 41169354, 2025). "Furthermore, 3-HBI suppresses Smad2/3 in TGF-β/Smad signaling, which suppresses breast cancer metastasis." (PMID 41009343, 2025). "In addition, SMAD3, SMAD6, and SMAD7 were lowly expressed in stage II breast cancer, while SMAD4 and SMAD2 were lowly expressed in stage III cancer." (PMID 38514720, 2024). "Importantly, SUMO-SnoN suppressed the ability of overexpressed Smad2 and Smad3 to promote EMT in breast carcinoma organoids." (PMID 37414747, 2023). "SMAD2 could be activated by the TGF-β1 signaling pathway, which, in turn, promotes KLF8 accumulation, leading to cancer progression in breast cancer." (PMID 36014967, 2022). "Breast cancer cells become more aggressive in the absence of Smad2 in part because Smad2 represses basal vascular endothelial growth factor A expression." (PMID 36549646, 2022). "Finally, by comparing the expression patterns of components of the TGF signaling pathway and KDM7A in human breast cancer specimens, we discovered that there was statistically significant correlation between KDM7A and TGFB2/SMAD2/SMAD3/SMAD4." (PMID 34249916, 2021). "Similarly, overexpression of miR-3613-3p decreased tumor proliferation and migration in TNBC cells via targeting SMAD2 and EZH2, EZH2 like SMAD2/3, significantly promoting cancer cell proliferation in many cancer cells, including breast cancer." (PMID 33916931, 2021). "PICK1 inhibits the binding of DICER1 to Smad2/3 and the processing of pre-miR-615-3p to mature miR-615-3p in breast cancer cells, thus exerting a negative feedback loop." (PMID 32336285, 2020). "It has been shown that inhibitors that decrease Smad2 and Smad3 levels by interrupting TGF-β signaling might be used for the treatment of human cancers, such as breast cancer and glioblastoma." (PMID 33330073, 2020).
breast carcinoma (continued). "Distinct effects of SMAD2 and SMAD3 were reported in breast cancer bone metastasis, pancreatic ductal adenocarcinoma cell proliferation and migration, HaCaT keratinocyte cell growth, TGF-β autoinduction in clostridium butyricum-activated dendritic cells and TGF-β induced transcription." (PMID 32746934, 2020). "Consistent with this, we observed a similar negative prediction value of Smad2 in the prognosis of breast cancer patients, although not statistically significant (right)." (PMID 32724475, 2020). "Moreover numerous targets of miR‐148a‐3p have been identified in breast cancer, including ALCAM, NRP1, SMAD2, and SPIN1, they mainly function in regulating cell growth, metastasis, and adhesion." (PMID 32508020, 2020). "Together, our data suggest that PICK1 inhibits the binding of DICER1 to Smad2/3 and the processing of pre-miR-615-3p to mature miR-615-3p in breast cancer cells, thus exerting a negative feedback loop." (PMID 32336285, 2020). "In turn, PICK1 inhibits the binding of DICER1 to Smad2/3 and the processing of pre-miR-615-3p to mature miR-615-3p in breast cancer cells, thus exerting a negative feedback loop." (PMID 32336285, 2020). "We reported it here that SND1 promotes the invasive and self-renewal capacity of breast cancer cells and increased sensitivity to Dox, which might be afforded by increased expression of SND1 downstream targets, SMAD2/3/4." (PMID 32117742, 2020). "Since Smad2 undergoes LOH in some cancers, it is considered as a tumor suppressor, which was supported by the observation that its expression at mRNA level was lower in invasive breast cancers compared to normal breast tissues." (PMID 31798766, 2019). "Treatment with ICI.182.780 or GREB1 knockdown increased PAI-1 mRNA expression in MCF7 breast cancer cells and GREB1 formed a complex with Smad2/3 in MCF7 cells, suggesting that GREB1 functions as a negative regulator of TGFβ signaling not only in HB but also breast cancer cells." (PMID 31462641, 2019). "Because TMEPAI is a Smad dependent TGF-β target gene and Smad3 but not Smad2 deficiency reduced TMEPAI levels, we tested the effect of R-Smad deficiency on cell migration and invasion of breast cancer cells by using Boyden chamber coated with matrigel." (PMID 31798766, 2019). "We then chose human breast carcinoma to explore the correlation of the expression levels of SIK with the levels of Par3 and the activity of the TGFβ pathway, measured as levels of phosphorylated Smad2 in the tumor tissue." (PMID 29464029, 2018). "miR-190 suppresses breast cancer metastasis and EMT phenotype by targeting SMAD2." (PMID 29510731, 2018). "However, curcumin at certain doses and times can inhibit TGF-β1 activity in regulating MMP-9 and activation of SMAD-2, ERK1/2, and p38 in breast cancer cells." (PMID 29445400, 2017). "Thus, CLDN6 is the key regulator in the SMAD2/DNMT1/CLDN6 pathway to inhibit EMT and migration and invasion of breast cancer cells." (PMID 28867761, 2017). "Therefore, inactivation of SMAD2 upregulated CLDN6 suppressed EMT, and subsequently inhibited the migration and invasion of breast cancer cells." (PMID 28867761, 2017). "We used immunostaining of phosphorylated Smad2/3 to assess TGF-β signaling activity in bone metastases from MDA-MB-231 breast cancer cells in mice treated or not treated with halofuginone." (PMID 29156807, 2017). "Our results show that SSA can inhibit the phosphorylation of Smad2/3 without interrupting total Smad2/3/4 levels in breast cancer cells." (PMID 26769851, 2016). "In summary, we have shown that AMPK by activation of metformin, AICAR, or LKB1 exerts a negative effect on TGF-β signaling, leading to inhibition of Smad2/3 activation and suppression of EMT and cell migration in breast cancer cells and precancerous mammary epithelial cells." (PMID 26718214, 2016). "Therefore, the objective of this study was to determine the mechanism of EGF-induced EMT through activating Smad2/3 in MCF-7 and MDA-MB-231 breast cancer cells." (PMID 27829223, 2016).
breast carcinoma (continued). "Moreover, FFLZ decreases the TGFβ-induced Smad2/3-Smad4-Snail/Slug-axis pathway and the expression of the EMT-related transcriptional factors in breast cancer cells." (PMID 27830743, 2016). "Taken together, these results indicate that 3D1 mAb treatment diminishes Nodal expression, as well as downstream phosphorylation of Smad2 and ERK1/2, and reduces Cyclin B1 while increasing p27 in melanoma cells and that similar effects can be observed in breast cancer cells." (PMID 26460952, 2015). "Although Smad2 and Smad3 are key elements in the Smad signaling pathway, they may play distinct roles in the induction of the EMT in breast cancer." (PMID 25962958, 2015). "This is interesting in light of previous reports indicating that overexpression of a dominant negative form of Smad3 reduced the ability of cancer cells to metastasize and that Smad3, but not Smad2, promotes breast cancer metastasis in mice." (PMID 22995475, 2012). "Furthermore, leptin was reported to stimulate the secretion of TGFβ, which leads to the activation of SMAD family member 2 (Smad2), Smad3, and Smad4 transcription factors, the repression of cadherin 1 (CDH1) coding for E-cadherin, and an increased CSC phenotype in breast cancer cells." (PMID 36010901, 2022). "However, the TFs such as KLF5 (52%), KLF1 (39%), and SMAD2::SMAD3::SMAD4 (31%) showed significant enrichment (q < 0.1) in gained peaks and FOX family of TFs (FOXA1 28%, FOXA2 28% and FOXF2 17%) in lost peaks in breast carcinomas." (PMID 34090364, 2021). "Moreover, PSG9 enhanced the stability of Smad2, Smad3, and Smad4 proteins by blocking their proteasomal degradation, and regulated the expression of TGF‐β1 target genes involved in EMT and breast cancer progression, thus further amplifying the canonical TGF‐β/Smad signaling in breast cancer cells." (PMID 33377651, 2020). "Furthermore, reduced LPP levels do not influence breast cancer cell proliferation or signalling responses induced by TGFβ, including phosphorylation of Smad2." (PMID 28436416, 2017). "Thus, we demonstrated that the downregulation of CLDN6 is regulated through promoter methylation by DNMT1, which depends on the SMAD2 pathway, and that CLDN6 is a key regulator in the SMAD2/DNMT1/CLDN6 pathway to inhibit EMT, migration and invasion of breast cancer cells." (PMID 28867761, 2017). "Furthermore, we examined the effects of blocking the Smad2/3 pathway in vivo and demonstrated that SB431542 applied to a breast cancer model could inhibit VM formation in xenografts." (PMID 27659524, 2016). "Consistent with our Nodal Western blot results, we found that Cerberus-Fc reduced p-Smad2 levels in Nodal expressing breast cancer cell lines, including MDA-MB-231 and BT549, but not in cell lines where we did not detect a Nodal signal, including T47D, MCF-7 and Hs57t." (PMID 25603319, 2015). "Additionally, TB activated immune-related pathways via ERK/MAPK signaling and upregulated genes such as SMAD2, SMAD3, and JUN.Conclusions: TB functions as an HSP90 inhibitor with dual anticancer and immunomodulatory properties in Estrogen Receptor-Positive (ER+) breast cancer cells." (PMID 41304910, 2025). "Here, the decrease of SMAD2 expression after HN1L gene silencing may be the result of the effect of HN1L gene silencing on cell proliferation and apoptosis, but the detailed molecular mechanism of HN1L regulating breast cancer cell proliferation needs to be further studied." (PMID 33191617, 2021). "Hence, Smad2 signaling could be activated in mammary cancers in the absence of TGF-β signaling, and this was likely due to the presence of activin." (PMID 28583174, 2017).